FGFR2 (fibroblast growth factor receptor 2)
Diseases named in the same sentence as FGFR2 in open-access papers (continued):
Sharing a sentence is not in itself a finding about the gene and the disease.
breast carcinoma (continued). "Furthermore, we propose that the phenotypic outcome of impaired FGF signalling caused by breast cancer mutations in the FGFR2 gene is further modified by genetic and environmental factors which remain to be discovered." (PMID 23527311, 2013). "Resistance of MCF-7 breast cancer cells to the anti-estrogen tamoxifen was associated with ERα-dependent overexpression of FGFR2, whereas resistance to fulvestrant was associated with ERα-dependent isoform switching, which correlated with altered response to KGF." (PMID 23758675, 2013). "Since FGFR signalling, and FGFR2 in particular, has been implicated as a driving force in breast cancer, over-expression of FGFR2 as a result of such alterations in transcriptional regulation was postulated as the underlying cause of the increased risk of developing breast cancer." (PMID 24265722, 2013). "However, several recent genome-wide association studies demonstrated that germ-line polymorphisms in intron 2 of FGFR2 are associated with breast cancer susceptibility emphasizing the importance of FGFR2 in breast cancer." (PMID 23300950, 2013). "The most notable associations among the ten previously GWAS-identified breast cancer susceptibility loci replicated in this study were with four FGFR2 SNPs (rs2981579, rs1219648, rs2420946 and rs2981582) and TNRC9-rs3803662 (observed P<7.0×10−10 and adjusted P<4.2×10−8)." (PMID 23717390, 2013). "Furthermore, both breast cancer mutations implicated an increased tyrosine phosphorylation of the critical FGFR2 substrate FRS2 and an increased MEK1/2 and STAT3 activation in response to FGF1 stimulation leading to an accelerated cell signaling." (PMID 23527311, 2013). "It is known that FGFR2 gene variations confer a risk for breast cancer." (PMID 23527311, 2013). "Rather, the observed increased risk of developing breast cancer might be the result of a coordinated effect of multiple SNPs forming a risk haplotype in the second intron of FGFR2." (PMID 24265722, 2013). "A breast cancer association was seen for six of the 14 tested SNPs; rs2981582 (FGFR2) 1.28 (1.12-1.47), rs3803662 (TNRC9) 1.20 (1.04-1.39), rs12443621 (TNRC9) 1.19 (1.04-1.35), rs889312 (MAP3K1) 1.18 (1.02-1.36), rs3817198 (LSP1) 1.17 (1.10-1.35) and rs2107425 (H19) 0.86 (0.75-0.99)." (PMID 22867275, 2012). "We found statistically significant evidence of association with breast cancer for eight of the 10 breast cancer susceptibility loci examined: FGFR2-rs2981582, TNRC9-rs3803662, 1p-rs11249433, 5p-rs7716600, 2q35-rs13387042, MAP3K1-rs889312, 8q24-rs13281615, and RAD51L1- rs999737." (PMID 22433456, 2012). "Two non-coding regulatory SNPs in FGFR2 affect binding of the transcription factors Oct-1/Runx2 and C/EBPβ, leading to an increased expression of FGFR2 in the rarer homozygous genotypes which have increased breast cancer risk." (PMID 22950704, 2012). "The risk allele locate at the intron 2 of the FGFR2 gene (rs2981582) represents 5–10% of breast cancer patients with estrogen receptor (ER)-positive tumor, whereas the SNP rs3803662 of TNRC9 gene seem to be correlated positively with bone metastases and ER-positive breast cancer patients." (PMID 22778704, 2012). "Despite this progress, substantial uncertainty remains regarding how subtle modulation of FGFR2 expression levels may modify breast cancer risk." (PMID 21767389, 2011). "The minor allele of FGFR2 SNP rs2981582 was associated with a significantly higher risk for PR-positive breast cancer for BRCA1 mutation carriers (per-allele HR for PR-positive = 1.29, 95% CI: 1.10 to 1.51, HR for PR-negative = 0.93, 95% CI: 0.87 to 1.00, P-heterogeneity = 7 × 10-4)." (PMID 22053997, 2011). "Furthermore, a large, three-stage GWAS of breast cancer had identified SNPs in FGFR2 as the strongest of its associations." (PMID 21853025, 2011). "Besides the three FGFR2 SNPs, three other SNPs in the top ten have been previously associated with breast cancer." (PMID 21853025, 2011).
breast carcinoma (continued). "Fine-scale genetic mapping and resequencing of the region surrounding rs2981582 resulted in the identification of up to eight variants in a linkage disequilibrium block (LD block) within intron 2 of FGFR2 most strongly associated with increased breast cancer risk, including SNP rs2981578." (PMID 21767389, 2011). "FGFR2 has been identified as a risk factor in breast cancer by association studies." (PMID 21108794, 2010). "Furthermore, genome-wide single-nucleotide polymorphism (SNP) analyses have identified SNPs in FGFR2 that result in increased susceptibility to breast cancer by elevating FGFR2 expression." (PMID 19410332, 2009). "Importantly, independent genome-wide association studies have associated other SNPs in FGFR2 with breast cancer." (PMID 19607694, 2009). "This suggests that the association with breast cancer risk may be mediated through differential levels of FGFR2 expression." (PMID 18437204, 2008). "In the ORIGO cohort, the minor allele of SNP rs2981582 in FGFR2 was found to correlate with a positive family history of breast cancer, defined as the ratio of the number of relatives with breast cancer and/or ovarian cancer relative to the total number of female relatives." (PMID 17997823, 2007). "GWASs have identified many single-nucleotide polymorphisms associated with breast cancer in intron 2 of FGFR2, and it has been hypothesised that the acetylation of the histones may affect access to the sites, possibly regulating downstream splicing sites, and generate the FGFR2 IIIc isoforms." (PMID 39596875, 2024). "In addition to hormone receptors, HER2 is also associated with FGFR2 in breast cancer." (PMID 39596875, 2024). "In addition, evidence in hormone receptor positive (HR+) breast cancers suggest potential roles for upstream receptor overexpression (FGFR2) and de novo mutations in RAS, AKT1, AURKA, CCNE2, and/or ERBB2 in the activation of ERK following acquired CDK4i/6i resistance." (PMID 38066089, 2024). "In addition, overexpression of NTRK3, EPHA7, and FGFR2 (M subtype-specific TK genes) has been linked to a worse prognosis in breast cancer and could promote TNBC formation." (PMID 36672350, 2023). "Intron 2 of the FGFR2 gene, highly conserved in mammals, has numerous possible transcription factor binding sites, some of which are positioned adjacent to the variants and speculated to be most strongly related to breast cancer." (PMID 37107577, 2023). "The authors stated that this association possibly can be due to the interaction of FGFR2 variants with high levels of endogenous sex hormones (FGFR2 is upregulated in ERα-positive breast tumors), especially estrogens, which may increase breast cancer risk." (PMID 26770289, 2016). "Subsequent analyses support their functional relevance to breast cancer risk that FGFR2 polymorphisms located in intron-2 alter the binding of two transcription factors, Oct-1/Runx2 and C/EBPb, resulting in an increase of FGFR2 gene expression both in cell lines and in breast tissue." (PMID 26421298, 2015). "Results of genotype analysis on the four selected FGFR2 intronic variants (rs2981582C/T, rs1219648A/G, rs2981578A/G, and rs7895676T/C) were available from 368 breast cancer cases/484 healthy controls and a notably significant association with breast cancer susceptibility was observed." (PMID 25333473, 2014). "Two SNPs (rs1219648 and rs2981582) lie within intron 2 of FGFR2 gene, encoding a receptor tyrosine kinase which participates in activation of signaling pathways engaged in tumor induction and progression and mediates breast cancer cell proliferation through D-type cyclins." (PMID 24171766, 2013). "Moreover, more than 20 common genetic variants have been shown to contribute to breast cancer risk; among these, the fibroblast growth factor receptor 2 (FGFR2) polymorphism rs2981582 as well as loci close to the cell cycle regulator Cyclin D1 (CCND1) at 11q13 are the most prominent risk loci." (PMID 23781229, 2013).
breast carcinoma (continued). "To determine whether the identified breast cancer mutation is primarily mediated by the FGFR2-IIIb or FGFR2-IIIc isoform, we examined the presence of the IIIb and IIIc transcripts in three cDNA samples synthesized from tumor tissue total RNAs of sporadic breast cancer patients." (PMID 23527311, 2013). "The mechanism by which FGFR2 functions as a risk factor in breast cancer, however, remains unknown." (PMID 23300950, 2013). "Therefore, it is speculated that the association with breast cancer is mediated through the regulation of FGFR2 expression." (PMID 23527311, 2013). "Our finding that individuals in whom intrinsically higher levels of FGFR2 are expressed in their skin fibroblasts also have higher levels of FGF10 suggests that the increased breast cancer risk might be due to a stronger paracrine effect between stromal and tumor cells involving FGF10 signaling." (PMID 21767389, 2011). "Previous studies have assessed whether SNP associations with breast cancer vary with ER status: rs2981582 (in FGFR2), rs3803662 in (TOX3), rs13387042 (in 2q35), and rs13281615 (in 8q24) were more strongly associated with ER-positive disease than ER-negative disease." (PMID 22087758, 2011). "FGFR2 amplification has been found in 7–23% of breast cancers, 5–10% of gastric cancers, and 12% of endometrial cancers." (PMID 41226813, 2025). "Multiple genetic aberrations in FGFR2, which activate upstream and/or downstream signaling pathways, have been identified in breast cancer." (PMID 41318657, 2025). "Studies focusing on biochemical and structural aspects indicate a marked increase in FGFR2 messenger RNA (mRNA) expression within breast cancer tissues compared to their normal counter parts." (PMID 40748883, 2025). "The study assessed how variations in the FGFR2 rs2981578 gene influence the likelihood of developing breast cancer among women with varying reproductive traits." (PMID 40748883, 2025). "In MDA-MB-231 breast cancer cells, neferine modulates miR-374a and FGFR-2 expression, influencing the PI3K/AKT and MEK/ERK signaling pathways to inhibit proliferation." (PMID 41154606, 2025). "Fibroblast growth factor receptor 2 (FGFR2) is an oncogenic driver in luminal breast cancer (BCa), with emerging evidence linking it to tumour immune microenvironment (TIME) modulation." (PMID 41018083, 2025). "Preclinical studies in FGFR2 driven cholangiocarcinoma and breast cancer indicate that FGFR inhibitors can down regulate RAD51 and sensitise tumours to platinum salts or to poly ADP ribose polymerase inhibitors." (PMID 41150770, 2025). "For instance, within the eRNA‐TWAS‐identified breast cancer susceptibility eRNA‐linked genes, two widely recognized breast cancer susceptibility genes, BRCA1 and FGFR2, were found to have statistically significant associations (FDR < 0.05)." (PMID 39950845, 2025). "Hence, the disparities noted in correlation analyses regarding the FGFR2 G/A polymorphism and breast cancer across various ethnic groups could arise from the interconnections between epigenetic modifications and polymorphism, thereby elucidating the intricate nature of genetic composition." (PMID 40748883, 2025). "Although FGFR2’s role in DDR is well established in cancers such as breast cancer and cholangiocarcinoma, its impact in GISTs is less characterized due to the low prevalence of FGFR2 alterations (1–2%)." (PMID 41150770, 2025). "FGFR1 amplifications are very common in many cancer types, including lung and breast cancer, whereas FGFR2-4 amplifications are less frequent, yet occurring e.g. in gastric and breast cancer." (PMID 40016412, 2025). "RPPH1 enhances breast cancer progression by stabilizing m6A-modified FGFR2 mRNA via IGF2BP2, activating PI3K/AKT signaling." (PMID 40565315, 2025). "The present study provides an insight into a novel aspect of FGFR2 involvement in the progression of breast cancer (BCa)." (PMID 41018083, 2025).
breast carcinoma (continued). "There is interest in FGFR2 as a possible target for therapeutics in various cancers, including breast cancer, increasing the need to understand the effects of FGFR2 on sustaining, and facilitating, the progression of cancer." (PMID 39596875, 2024). "For example, FGF7, FGF10, and FGF22 bind exclusively to FGFR2 IIIb, with FGFR2 IIIb/FGF10 being highly associated with breast cancer development." (PMID 39596875, 2024). "Comparing the FGFR2 gene expression in the breast cancer subtypes, the mRNA expression was highest in luminal-A and luminal-B tumours, slightly lower in basal-like tumours, and significantly lower in HER2-enriched tumours." (PMID 39596875, 2024). "This suggests that an increased FGFR2 expression is related to maintaining the epithelial expression of breast cancer, whereas a lower FGFR2 is expressed in more aggressive forms of breast cancer." (PMID 39596875, 2024). "In contrast, a more recent work proposed a pore-dependent function for TRPA1 in lung and breast cancer pro-survival signaling, which seems to exclude FGFR2 involvement." (PMID 38339360, 2024). "The epithelial alternatively spliced FGFR2 IIIb isoform was significantly enriched in ER+ breast cancer, while the mesenchymal FGFR2 IIIc isoform was significantly prevalent in HER2+ cancer." (PMID 39596875, 2024). "FGF signaling served as a key player in breast cancer progression, and FGFR1 and FGFR2 are known to be the most common genetic mutations." (PMID 39796710, 2024). "The amplification of FGFR1 represents the most frequent genomic alteration in breast cancer, with FGFR2-4 gene amplifications being less commonly seen." (PMID 38255923, 2024). "Among these FGFR inhibitors, Erdafitinib, a selective and irreversible pan-FGFR inhibitor, has demonstrated significant antitumor activity in the FGFR2-amplification subset in breast cancer." (PMID 39796710, 2024). "FGFR2 amplification is less frequent, occurring in 5 to 10% of gastric cancer (particularly invasive diffuse subtype 2) and 2% of breast cancer, with approximately 4% of triple-negative breast cancer cases showing amplification." (PMID 39583123, 2024). "FGFR2 expression was higher in ER+ breast carcinomas than ER− cancers, confirming what was seen in the subtype analysis." (PMID 39596875, 2024). "A further interrogation of our data showed that the expression of FGFR2 mRNA was higher in ER+ than ER− breast cancers." (PMID 39596875, 2024). "Given the various complex roles that FGFR2 plays in EMT, and its high association with breast cancer in GWASs, we wish to investigate its expression in breast cancer." (PMID 39596875, 2024). "GP369, a monoclonal antibody directed against the extracellular ligand-binding structural domain of FGFR2, showed promising results in FGFR2-IIIb subtype of breast cancer cell lines, demonstrating inhibition of tumour proliferation." (PMID 40135140, 2024). "In breast cancer, FGFR2 promotes hormone-independent tumour growth and progression, the inhibition of apoptosis, and resistance to endocrine therapies." (PMID 39596875, 2024). "EGFR KDD was first identified in colorectal cancer and breast cancer, whereas FGFR2 KDD was first identified in gastric cancer." (PMID 36325957, 2023). "Additional in silico analyses comparing breast cancer and adjacent normal tissue showed significantly downregulated expression of FGFR2 and ITGB1 in tumour samples." (PMID 37191822, 2023). "CAF-derived FGF7 was shown to promote ER phosphorylation and breast cancer cell growth through FGFR2, which ultimately reduced the efficacy of endocrine therapies." (PMID 37800138, 2023). "For example, three loci—MYEOV (rs10737153), TNS1 (rs201030469) and FGFR2 (rs17102399)—have impacts on both PRC layer thickness and risk of diagnosis for breast cancer." (PMID 36848389, 2023). "Breast cancer tissues had considerably more significant levels of FGFR2 mRNA expression than normal tissues (p < 0.01)." (PMID 37107577, 2023).
breast carcinoma (continued). "Although FGFR1 and FGFR2 fusions were less frequent overall, FGFR1 was relatively common in breast cancer (0.4%) and FGFR2 in hepatobiliary/hepatocellular cancer (4.3%)." (PMID 37537783, 2023). "The GEPIA and UALCAN databases revealed that breast cancer tissues possess greater levels of FGFR2 mRNA expression than normal tissues (p < 0.01)." (PMID 37107577, 2023). "Although we did not have sequencing data available from the original tumor of patient #26, the #26 PDO had mutations typically present in breast cancer, such as mutations in BRCA2, FGFR2, and PMS2." (PMID 37423299, 2023). "For example, FGFR1 is amplified in lung and breast cancers and rarely in pancreatic and squamous cell lung cancers, whereas FGFR2 amplification mainly occurs in gastric and breast cancers." (PMID 38282676, 2023). "MAP kinase MEKK1, coded by MAP3K1, has been reported to promote cancer cell migration by contributing to an accommodating breast tumor microenvironment, while FGFR2 has been identified as a viable drug target in breast cancer." (PMID 36703164, 2023). "Futibatinib treatment led to significant growth inhibition in models with FGFR2 amplification, further supporting the rationale for this alteration being pursued in a phase II breast cancer trial (NCT04024436)." (PMID 37980453, 2023). "The coiled coil domain was found in FGFR2::CCDC6 (breast cancer, iCCA), FGFR2::CIT (lung carcinoma), and FGFR2::KIAA1967 (lung squamous cell carcinoma) fusions, all of which exhibited constitutive dimerization." (PMID 37370984, 2023). "TAF produce and secrete high fibroblast growth factor 5 (FGF5) to activate fibroblast growth factor receptor 2 (FGFR2) in surrounding breast cancer cells." (PMID 37174034, 2023). "FGFR2 maintains a population of tumour-initiating cells in mice, and claims have been made that FGFR2 can be targeted to eliminate breast cancer stem cells." (PMID 35193394, 2022). "The FGFR2 gene is located on the 10q26.13 chromosomal region, which is amplified in only 5% of all breast cancer patients, in particular TNBC patients." (PMID 35193394, 2022). "FGFR2 amplification gave positive results in gastric cancer but disappointed in, e.g., breast cancer or NSCLC." (PMID 36231142, 2022). "RFS analysis suggested that patients with breast cancer having low mRNA levels of FGFR2 had significantly worse RFS relative to the other groups (p = 0.04), whereas patients with high levels of ERBB4 had a better RFS than the opposite group (p = 9.5 × 10-5)." (PMID 36601474, 2022). "FGF3 levels correlate with stage and grade, FGFR2 signalling activation and proliferation of breast cancer cells." (PMID 35193394, 2022). "The first studies on the role of FGFR in breast cancer identified the amplification of FGFR1 and FGFR2 genes in human breast cancer samples." (PMID 35193394, 2022). "Patients with breast cancer showing low levels of FGFR2 and ERBB4 had worse OS relative to the other groups (p = 0.022)." (PMID 36601474, 2022). "We have recently demonstrated that fibroblast growth factor receptor 2 (FGFR2)‐mediated signalling alters progesterone receptor (PR) activity and response of oestrogen receptor α (ER)‐positive (ER+) breast cancer (BCa) cell lines to anti‐ER agents." (PMID 35726195, 2022). "In particular, homologs AKT1, AKT2, ERBB2, FGFR2, and PIK3CA in CGC play important roles in breast cancer progression, mediating breast cancer risk, corresponding to the driver candidates RPS6KA1, SGK1, PTK2, IGF1R, PIK3CB, and PRKDC predicted by DriverMP." (PMID 38091511, 2022).